PCNA (proliferating cell nuclear antigen)
Diseases named in the same sentence as PCNA in open-access papers (continued):
Sharing a sentence is not in itself a finding about the gene and the disease.
cancer (650 papers, 1995 to 2026). A tumor composed of atypical neoplastic, often pleomorphic cells that invade other tissues. "AOH1996 is a novel small molecule inhibitor of cancer-associated Proliferating Cell Nuclear Antigen (PCNA)." (PMID 41982673, 2026). "Inflammation is also a known risk factor for cancer progression via activating cell proliferation through proliferating cell nuclear antigen (PCNA), a marker of cell proliferation crucial for DNA synthesis and repair." (PMID 41307829, 2025). "IHC for PCNA and αSMA revealed that Hep-53.4 tumors are highly proliferative and include a significant population of activated cancer-associated fibroblasts." (PMID 40377490, 2025). "PCNA is closely associated with cancer initiation and progression and serves as a target in anticancer therapy." (PMID 41024256, 2025). "The strong association between PCNA expression and cancer progression has driven extensive research into its therapeutic potential, with PCNA-targeted therapies under investigation to enhance treatment outcomes across various cancers." (PMID 41170373, 2025). "Loss of Y211 phosphorylation in PCNA impairs cancer stemness, showing reduced ALDH activity and inhibited tumorsphere formation." (PMID 41024256, 2025). "The translesion DNA synthesis (TLS) pathway mediated by proliferating cell nuclear antigen (PCNA) monoubiquitination is an essential mechanism by which cancer cells bypass DNA damage caused by DNA damage to maintain genomic stability and cell survival." (PMID 40025006, 2025). "PCNA overexpression is a hallmark of cancer virulence and promotes cancer survival via several mechanisms, including immune evasion through inhibition of NKp44-mediated NK cell attack." (PMID 38504978, 2024). "Colonic cells incubated with S. gallolyticus showed elevated levels of β-catenin, c-MYC, and proliferating cell nuclear antigen (PCNA), which are transcription factors linked to cancer development." (PMID 39726700, 2024). "We report on AOH1996 (AOH), an oral compound targeting cancer-associated PCNA, which shows significant antileukemic activity." (PMID 39732733, 2024). "TAMs that have a population of cytosolically expressed PCNA are associated with poor prognosis for cancer patients." (PMID 39205238, 2024). "The association of PCNA in cancer has led to many considering the significance of its role within cancer cells." (PMID 39205238, 2024). "The decrease in PCNA mRNA indicates a reduction in cell proliferation or DNA damage, another cancer hallmark." (PMID 38227157, 2024). "Although PCNA is ubiquitously present in all cells, it is overexpressed in most cancers and associated with cancer virulence." (PMID 39205238, 2024). "Proliferating cell nuclear antigen (PCNA) is a well-documented protein that is frequently overexpressed in the nuclei of cancer cells, and this overexpression has been linked to increased cancer virulence." (PMID 37686697, 2023). "That finding, together with the currently presented co-expression of PCNA and megalin in cancer cells, underlines the pro-proliferative role of the molecule concerned." (PMID 37185704, 2023). "It appears that ZBSO inhibits cancer through the downregulation of PCNA protein and pathways associated with CDC25A/CyclinB1/CDK1." (PMID 37081962, 2023). "Most of the down-regulated hub proteins (ESR1, MCL1, LCK, TBP, and PCNA) play roles in the proliferation or survival of cancer cells, and CHEK1 is associated with the cell cycle checkpoint in cancer cells." (PMID 35563525, 2022). "It would be necessary to continue studying the diversity and functionality of the PCNA transcript variants expressed in healthy individuals and cancer patients." (PMID 36291073, 2022). "To determine the malignant characteristics of PCNA V3 and V4 variants in vitro and identify a good model of knockdown, we analyzed the mRNA expression in 25 cancer cell lines by means of quantitative RT-PCR." (PMID 36291073, 2022).
cancer (continued). "It has been shown that PCNA expression levels change during cell cycle, as PCNA is associated with proliferation and cell transformation in cancer." (PMID 36142875, 2022). "Anti‐Chi3L1 antibody significantly decreased the expression of cancer growth and migration‐associated proteins, such as PCNA, cyclin D1, cyclin E, Cdk2, Cdk4, Cdk5, MMP2 and MMP9 in A549 lung metastasis model tissues." (PMID 34861103, 2022). "Another PCNA inhibitor PCNA-I1S was found to selectively bind PCNA, suppress its chromatin association, and to suppress cancer cell growth." (PMID 34572827, 2021). "Cells from prostate cancer, hepatic carcinoma, high-grade prostatic intraepithelial neoplasia, and neuroblastoma also had the unique PCNA isoform associated with cancer." (PMID 34831131, 2021). "PCNA, which encodes proliferating cell nuclear antigen, is an essential factor in DNA replication and many other cancer cell processes, especially in cell proliferation." (PMID 34079762, 2021). "The cancer-associated isoform of PCNA (caPCNA) was likely from post-translational modifications and not from genetic mutations or alternate splicing." (PMID 34831131, 2021). "FEN1 has been observed overexpressed in a broad spectrum of cancers and was previously associated with PCNA-dependent genetic instability and DNA damage." (PMID 34616685, 2021). "Since IGF1R/PCNA interaction was associated with better outcome in the two clinical cancer cohorts, we sought to identify its functional role in cell lines." (PMID 32701997, 2020). "This would be reminiscent of the cancer-associated isoform of proliferating cell nuclear antigen (PCNA)." (PMID 31573152, 2019). "A peptide derived from the unique region of cancer-associated PCNA was cytotoxic towards cancer cells but considerably less so towards normal cells." (PMID 31573152, 2019). "The top five upregulated DEGs, including CDK1, CCNB1, TOP2A, MYC, and PCNA, were associated with cell mitosis and involved in the development of cancer." (PMID 30092828, 2018). "By generating sets of tumors proficient or deficient in PCNA ubiquitination, we put this concept to the test and provided concrete basis for future cancer intervention strategies." (PMID 29721165, 2018). "Because the R9-cc-caPeptide is specific to cancer-associated PCNA, it is targeted to cells containing only this isoform and thus has less of an effect on normal cells." (PMID 30406112, 2018). "A unique form of PCNA, termed cancer-associated PCNA (caPCNA) was identified in these cells that is different from PCNA in normal breast cells due to a post-translational modification, specifically methyl esterification of glutamic and aspartic acids residues." (PMID 30406112, 2018). "FEN1 mutations that specifically disrupt the PCNA interaction have been reported to cause aneuploidy‐associated cancer progression." (PMID 28371273, 2017). "Expression of PCNA is associated with the expression of epidermal growth factor receptor, which itself is a survival factor for many cancers, including RCC." (PMID 28405545, 2017). "The critical involvement of PCNA in cellular proliferation and its tight association with transformation in cancer have resulted in its significant importance and application in the clinic." (PMID 28878179, 2017). "One salient feature of our data is the association between cytosolic PCNA and proteins from the glycolysis pathway that has been already identified as a critical pathway for cancer therapy." (PMID 27759041, 2016). "Paf15 (also known as KIAA0101, NS5ATP9, OEACT-1, and L5), is a 12-kDa proliferating cell nuclear antigen (PCNA) - associated protein that is involved in cancer development and progression." (PMID 27246972, 2016).
cancer (continued). "A series of PCNA-I1 analogs were obtained from the UC-DDC compound library or commercial sources and evaluated in assays for PCNA trimer stability in vitro, growth inhibitory effects in four cancer cell lines, and the level of chromatin-associated PCNA." (PMID 25729582, 2015). "The four tested cancer-associated mutants readily decreased HU-induced PCNA ubiquitination in 293T cells." (PMID 25744535, 2015). "The p15PAF/KIAA0101 protein is a proliferating cell nuclear antigen (PCNA)-associated protein overexpressed in multiple types of cancer." (PMID 23593430, 2013). "Expression of PCNA is typically restricted to replicating cells; however, over expression of PCNA is often associated with cancer formation and progression, but also normal development in the deciduas of pregnant women, contributing to NK cell tolerance." (PMID 23527218, 2013). "The tight association of PCNA with cancer transformation resulted in the use of PCNA as a diagnostic and prognostic cell cycle marker in tumors." (PMID 23181059, 2012). "PCNA is critical during chromosomal DNA replication; it has been found to be overexpressed in various types of cancers and that its expression is associated with poor survival outcomes." (PMID 20140087, 2010). "Predictive biomarkers, such as the cancer-associated PCNA isoform and replication stress signatures, may help refine patient selection." (PMID 41170373, 2025). "As hypothesized by us, the PIR peptide achieved global S-Pol displacement from PCNA-associated replication factories and enhanced the cancer cell killing potential of DNA damaging agents including cisplatin, hydroxyurea, olaparib and UV irradiation." (PMID 40628724, 2025). "Our study hence highlights those mutations at the interface between Polε and PCNA may also affect its proofreading activity and could be involved in cancer progression." (PMID 40291687, 2025). "Thesefindings underline PCNA’s multifaceted role in cancer development,which may differ depending on the cancer-type context." (PMID 40657100, 2025). "Elevated PCNA levels are associated with poor prognosis in various cancers." (PMID 40313621, 2025). "In addition, another study found an association between chemotherapy resistance, cancer cell survival, and PCNA." (PMID 39205238, 2024). "In particular, the discovery of the cancer-associated isoform of PCNA (caPCNA) and the development of small molecule and peptide agents that specifically target caPCNA allows for the selective targeting of cancer cells without causing significant toxicity to normal cells or experimental animals." (PMID 37510250, 2023). "Furthermore, PCNA has been reported as a promising diagnostic tool and prognostic indicator for evaluation of cancer therapy and disease progression." (PMID 37861934, 2023). "The proliferating cell nuclear antigen (PCNA) gene encodes two transcripts for the same protein of 261 amino acids, which is associated with several important cellular processes and with several types of cancer." (PMID 36291073, 2022). "Interestingly, PCNA is a cancer-associated nuclear factor that exists as a homotrimer to form a clamp around nuclear DNA and promote replication." (PMID 35563109, 2022). "Patients with high levels of PCNA are linked with poor overall survival rates in breast, ampulla of Vater, non-small-cell lung, and pancreatic ductal adenocarcinoma cancer." (PMID 34831131, 2021). "Elevating levels of chromatin-bound PCNA may thus help target cohesinopathic cells linked that are linked to cancer." (PMID 33075068, 2020).
cancer (continued). "Natural and synthetic small molecules from the NCI Developmental Therapeutics Program (DTP) were employed in molecular dynamics-based docking with DNA repair proteins whose RNA-Seq based expression was associated with overall cancer survival (OS) after adjustment for the PCNA metagene." (PMID 30759820, 2019). "Thus, for example, increased expression of the anti-apoptotic protein B-cell lymphoma 2 (BCL-2) and proliferating cell nuclear antigen (PCNA) has been linked to Wnt3a in cancer cells." (PMID 31827403, 2019). "Mutations in FEN1 that disrupt its interaction with PCNA also induce aneuploidy-associated cancer." (PMID 31402791, 2019). "Membrane expression of PCNA was shown to be associated with HLA-I expression on cancer cell lines." (PMID 29875773, 2018). "Here we explore the role of cell proliferation across 19 cancers (n = 6,581 patients) by using tissue-based RNA sequencing data from The Cancer Genome Atlas Project and calculating a ‘proliferative index’ derived from gene expression associated with Proliferating Cell Nuclear Antigen (PCNA) levels." (PMID 28454104, 2017). "Importantly, in this group of cancer patients, markers of cell proliferation (Ki67 and PCNA) were associated with poor overall survival, as would be expected." (PMID 28978099, 2017). "In agreement with previous studies, we observed that kaempferol inhibited cell growth by causing apoptosis of cancer cells through the decreased PCNA and cleaved caspase-3 pathway; this inhibition of cancer cells was achieved by administering kaempferol in different dosages." (PMID 27175782, 2016). "PCNA over-expression is abundant in cancers and is directly associated with cancer virulence." (PMID 27102296, 2016). "It is reported that PCNA was one of the Hsp90 client proteins in HCT-116, suggesting that the association of PCNA with Hsp90 might be a general phenomenon in cancer cells." (PMID 27832777, 2016). "We next tested the ability of these cancer-associated USP1 mutants to deubiquitinate PCNA." (PMID 25744535, 2015). "The PCNA protein can be associated with the cellular activity in cancer cells." (PMID 26610484, 2015). "To summarize, it appears that our data associate the disruption of the DNMT1/PCNA interaction with the presence of a global DNA hypomethylation phenotype, the acquisition of several cancer phenotypes, the hypomethylation of certain genes and with the presence of chromosomal aberrations." (PMID 24637615, 2014). "The increased expression of PCNA in cancer patients has been associated with a poor survival rate." (PMID 24124611, 2013). "Moreover, the study is based on preliminaryfindings associating PCNA to cancer development." (PMID 40657100, 2025). "Therefore, the ability of R11-NLS-pep8 to penetrate the cancer cell and interact with intracellular PCNA could potentially be reduced by interaction with cell membrane- or exosome-associated PCNA." (PMID 29875773, 2018). "Moreover, PCNA is also the basic component of recombination-associated DNA synthesis during the process of double-strand break repair in chemoresistant cancer or after treatment with platinum-based cancer drugs." (PMID 28562655, 2017). "Since NKp44 also recognizes heparan sulfate proteoglycans as co-ligands, it was suggested that NKp44 could recognize cancer cell-produced damage-associated molecular patterns (DAMP) that can either activate (if containing MLL5) or inhibit (if containing PCNA and MHC class-I) NK cell function." (PMID 27102296, 2016). "Given the versatile functions of PCNA in maintaining the integrity of the genome, further exploration of the underlying mechanisms of these functions can lead to a better understanding of how cell signaling in the nucleus shapes the dynamics of genomic stability in cancer cells." (PMID 22238610, 2012).
cancer (continued). "It disrupts DNA replication and repair by enhancing PCNA-RPB1 interactions, dissociating PCNA from transcribed chromatin, and inducing DNA double-strand breaks (DSBs), resulting in selective toxicity of various cancer types." (PMID 41982673, 2026). "Proliferating cell nuclear antigen (PCNA) is a critical regulator of DNA replication and repair, and its cancer-associated isoforms represent promising therapeutic targets." (PMID 41828847, 2026). "Targeting PCNA in cancer therapy has been a long-standing challenge, but recent advancements have opened new avenues for exploration." (PMID 41170373, 2025). "AOH1160 and AOH1996 are also small-molecule compounds that target PCNA and have demonstrated promising anti-cancer activity." (PMID 41024300, 2025). "PCNA has also been shown to play a vital role in cell proliferation, and has been considered as a potential target of cancer therapy." (PMID 40284877, 2025). "Our studyorients the first comprehensive pan-cancer analysis of PCNA, uncoveringits prognostic significance and altered expression across variouscancers through multiomics data." (PMID 40657100, 2025). "PCNA remains an attractive target because of its central role in cancer proliferation, yet this same universality raises concerns about on-target toxicity in normal tissues." (PMID 41170373, 2025). "By targeting this region, AOH1160 blocked PCNA interactions, leading to apoptosis in cancer cells due to failed DNA replication and repair." (PMID 41170373, 2025). "Cancer cell proliferation is often related to proliferating cell nuclear antigen (pCNA), which is involved in the important metabolism of cancer cells, such as cell survival, energy metabolism, glycolysis." (PMID 39944835, 2025). "As a marker of cell proliferation, the expression level of PCNA is generally correlated with the proliferative activity and prognosis of cancers." (PMID 41132724, 2025). "This discovery revolutionized PCNA-targeted therapy by allowing selective inhibition of cancer cells, reducing off-target toxicity, and potentially minimizing acquired drug resistance." (PMID 41170373, 2025). "In 2012, researchers identified Y211 phosphorylation of PCNA as a marker for prostate cancer and developed a synthetic Y211F peptide to inhibit this modification, which enhanced cancer cell death." (PMID 41170373, 2025). "PCNA is a well-established target in cancer therapy due to its critical involvement in cell proliferation, DNA replication, and repair." (PMID 41170373, 2025). "PCNA mRNA levels were altered in across cancers andassociated with altered cancer signaling networks constituting Wnt,Hippo, and mTOR pathways." (PMID 40657100, 2025). "PCNA is highly expressed in many cancers and contributes to malignant proliferation and poor prognosis." (PMID 40313621, 2025). "ln the results, METTL16 was positively correlated with the expression of MKI67 and PCNA among most types of cancer." (PMID 40015977, 2025). "Cancer therapies that inhibit these DDR pathway processes and associated proteins, such as PCNA, 53BP1, and BRCA, among others, result in elevated DNA damage and cancer cell death." (PMID 40282554, 2025). "They exerted their effect through various mechanisms such as apoptosis induction, metastasis and angiogenesis inhibition and decreased several cancer biomarkers such as ki-67, proliferating cell nuclear antigen (PCNA) and matrix metalloproteinases (MMP)." (PMID 41322296, 2025). "Nevertheless, drugs such as Trametinib, RDEA119, andSelumetinib demonstrated a positive relationship with PCNA expression,signifying therapeutic resistance in cancer." (PMID 40657100, 2025). "The CRC-bearing rats treated with PGPs-NE exhibited normalized metalloproteinase activity, stable biomarkers for cancer and inflammation, improved liver function, increased antioxidant levels, reduced levels of fragmented DNA, and PCNA expression." (PMID 41307829, 2025).